PANK1 (pantothenate kinase 1)
Diseases named in the same sentence as PANK1 in open-access papers:
PANK1 is named in the same sentence as 46 diseases in open-access papers, as found by Europe PMC text mining. Sharing a sentence is not in itself a finding about the gene and the disease. The quoted sentences say what the papers report.
malaria (6 papers, 2016 to 2025). Malaria is a serious and sometimes fatal disease caused by a parasite that commonly infects a certain type of mosquito which feeds on humans. "Here, we show the selection of nonsynonymous mutations in malaria parasites' druggable kinases: the PANK1, DAGK, and PI4Kβ." (PMID 38915420, 2022). "We reveal sequence conservation and unique ligand-binding motifs in the CK, PANK1, DAGK, PI4Kβ, and CDPK1 across malaria species." (PMID 38915420, 2022).
hyperglycaemia (4 papers, 2010 to 2024). "This is reinforced by mutations in PANK1 being linked with hyperglycaemia." (PMID 28863176, 2017). "The findings also suggest that PanK1 may be a suitable target for therapeutic intervention in metabolic disorders that feature hyperglycemia and hypertriglyceridemia." (PMID 20559429, 2010).
diabetes (3 papers, 2017 to 2020). "Mutations of the PanK1 and PanK2 genes are associated with PanK-dependent neurodegeneration (PKAN) and diabetes." (PMID 28832533, 2017). "Moreover, in ob/ob mice (well-established models of human type 2 diabetes mellitus (DM2)), PANK1 deficiency leads to reduced serum insulin, improved insulin tolerance, and reduced fasting blood glucose." (PMID 33260564, 2020).
steatosis (3 papers, 2010 to 2022). Increased lipid within the cytoplasm of cells. "Upon 2 weeks WD challenge, hepatic PANK1-deficient mice developed worsened steatosis with ~2-fold higher hepatic triglyceride (TG) and cholesterol content than controls, which could be prevented by TFEB overexpression." (PMID 36171419, 2022). "Like the Pank1−/− mice, this partial fatty acid oxidation defect gives rise to fasting steatosis and hypoglycemia with normal ketogenesis." (PMID 20559429, 2010).
colorectal cancer (2 papers, 2018). A primary or metastatic malignant neoplasm that affects the colon or rectum. "For colorectal cancer, an exhaustive search revealed the FASTKD2, PANK1, and HUWE1 gene triple from the core to have the highest prognostic power (with respect to the training and filtration datasets)." (PMID 29402894, 2018).
hepatocellular carcinoma (2 papers, 2022 to 2024). A malignant tumor that arises from hepatocytes. "PANK1 can inhibit hepatocellular carcinoma by regulating Wnt/β-catenin and modulating the cell cycle." (PMID 38893707, 2024). "Of these 8 kinases, GALK1, PCK1 and PANK1 were highly expressed in normal liver tissues and down-regulated in hepatocellular carcinoma (HCC)." (PMID 35280671, 2022).
Hypoglycemia (2 papers, 2010 to 2012). A decreased concentration of glucose in the blood. "Previously, adult Pank1(−/−) mice were found to exhibit reduced hepatic CoA levels, a reduced rate of CoA-dependent fatty acid oxidation in the fasted state, impaired gluconeogenesis, and mild hypoglycemia in the fasted state." (PMID 22815849, 2012). "Pank1 gene deletion in mice results in a metabolic phenotype where fatty acid oxidation and gluconeogenesis are impaired in the fasted state, leading to mild hypoglycemia." (PMID 22815849, 2012).
acute myeloid leukemia (1 paper, 2023). Acute myeloid leukemia (AML) is a group of neoplasms arising from precursor cells committed to the myeloid cell-line differentiation. "Few studies already suggested that the levels of PANK1 and 2, but not 4, isoforms, known to positively regulate CoA rate of synthesis, were positively associated with a better outcome in clear cell renal cell carcinoma and acute myeloid leukemia, respectively." (PMID 37833072, 2023).
adenoma (1 paper, 2024). A neoplasm arising from the epithelium. "We further validated that the region containing rs140356782 significantly interacted with PANK1 promoter in our colorectal tissues spanning normal to advanced adenoma to cancer using Hi-C assay." (PMID 38872215, 2024).
asthma (1 paper, 2022). "Our findings highlight VCAM1, EXTL2, and PANK1 as functional loci for asthma exacerbations applicable to people across different ancestral backgrounds, warranting future investigation of these novel genomic mechanisms underlying asthma exacerbations." (PMID 35754128, 2022).
brain tumors (1 paper, 2023). "Analysis showed that PANK1 expression was significantly downregulated in malignant brain tumors compared with normal brain tissues." (PMID 37138430, 2023).
cholangiocarcinoma (1 paper, 2018). A carcinoma that arises from the intrahepatic biliary tree (intrahepatic cholangiocarcinoma) or from the junction, or adjacent to the junction, of the right and left hepatic ducts (hilar cholangiocarcinoma). "We obtained in vivo evidence for deregulation of this tumor suppressive mechanism in human cholangiocarcinomas, where several genes involved in taurine-mediated volume regulation (GABRB3, PANK1 and LRRC8a) were repressed." (PMID 29787571, 2018). "Stratifying the cohort of 104 cholangiocarcinomas for RNA expression above and below the mean revealed that low RNA expression of GABRA5, LRRC8a, ADO and PANK1, but not GABRB3, was associated with reduction of the median survival time of patients by 1.8, 2.1, 3.3, and 4.3 years, respectively." (PMID 29787571, 2018). "Microarray-based expression profiling of 104 resected human cholangiocarcinomas revealed reduced expression of GABRB3, PANK1, and LRRC8A, but not GABRA5 or ADO, compared to micro-dissected bile duct controls." (PMID 29787571, 2018).
glioblastoma (1 paper, 2023). The most malignant astrocytic tumor (WHO grade IV). "Besides, both lower-grade glioma (LGG) and glioblastoma multiform (GBM) patients with high expression of PANK1 had a significantly better prognosis than those with low expression of PANK1 in TCGA, Gravendeel and Rembrandt datasets (all P <0.01)." (PMID 37138430, 2023). "PANK1 plays an important role in mediating CoA biosynthesis; therefore, PANK1 expression may be correlated with the occurrence, development, and prognosis of glioblastoma." (PMID 37138430, 2023). "IHC analysis of 38 glioblastomas (GBM, WHO IV) tissues and 18 lower-grade glioma tissues (LGG, WHO I-III) showed that the PANK1 expression level was lower in GBM compared with that in LGG." (PMID 37138430, 2023).
glioma (1 paper, 2023). A benign or malignant brain and spinal cord tumor that arises from glial cells (astrocytes, oligodendrocytes, ependymal cells). "Lower PANK1 expression is associated with a worse prognosis of glioma patients, indicating that PANK1 is a novel prognostic biomarker in glioma patients." (PMID 37138430, 2023). "Multivariate Cox regression analysis showed that low expression of PANK1 was an independent factor associated with short overall survival in glioma patients in TCGA dataset." (PMID 37138430, 2023). "Multivariate Cox regression analysis revealed that low PANK1 expression was an independent risk factor associated with a worse prognosis of glioma patients." (PMID 37138430, 2023). "Therefore, it is important to explore the molecular mechanisms underlying PANK1 expression in the glioma malignancy process to help identify novel therapeutic targets for glioma." (PMID 37138430, 2023). "PANK1 is implicated in regulating the extracellular matrix and analysis showed that PANK1 may be a crucial gene involved in regulating the proliferation and invasion of glioma cells." (PMID 37138430, 2023). "The decreased expression levels of PANK1 were found to be significantly correlated with poor prognosis of glioma, implying that it is a potential biochemical marker in glioma." (PMID 37138430, 2023). "The findings of the present study provide a new perspective on the functions of PANK1 in glioma cells." (PMID 37138430, 2023). "Transwell assay showed that overexpression of PANK1 significantly decreased the invasive capacity of glioma cells." (PMID 37138430, 2023). "IHC staining was performed to further explore the relationship between PANK1 expression and glioma grade." (PMID 37138430, 2023). "Analysis of TCGA, CGGA and Gravendeel datasets showed significantly lower PANK1 mRNA expression level in the IDH-wildtype (WT) compared with the level in the IDH-mutant (Mut) gliomas in all grades." (PMID 37138430, 2023). "High expression of PANK1 is correlated with significantly better prognosis of glioma patients compared to glioma patients with low expression levels of PANK1." (PMID 37138430, 2023). "PANK1 expression is downregulated in glioma tissues and is a novel prognostic biomarker in glioma patients." (PMID 37138430, 2023). "Kaplan–Meier and Cox regression analyses were used to explore the relationship between PANK1 and prognosis in glioma." (PMID 37138430, 2023). "The findings of this study showed that PANK1 expression was significantly downregulated in glioma tissues compared to normal brain tissues." (PMID 37138430, 2023). "In summary, PANK1 expression is downregulated in glioma tissues and is negatively correlated with tumor malignancy." (PMID 37138430, 2023). "In addition, the PANK1 expression level decreased with an increase in glioma grade and tumor malignancy progression." (PMID 37138430, 2023). "However, further studies should explore the mechanism of action of PANK1 in promoting glioma cell invasion." (PMID 37138430, 2023). "Furthermore, high expression of PANK1 was correlated with significantly better prognosis of glioma patients compared to patients with low expression of PANK1 (all P<0.01 in the four datasets)." (PMID 37138430, 2023). "IHC was performed to further explore the role of PANK1 in glioma." (PMID 37138430, 2023). "PANK1 may promote glioma cell invasion by regulating tumor cell metabolism." (PMID 37138430, 2023). "Public datasets (The Cancer Genome Atlas (TCGA), Chinese Glioma Genome Atlas (CGGA), Gravendeel and Rembrandt) and validation cohort were used to explore the expression of PANK1 in glioma tissues." (PMID 37138430, 2023). "Moreover, PANK1 may be a key regulator of the proliferation and invasion of glioma cells." (PMID 37138430, 2023). "In this study, PANK1 was significantly differentially expressed in IDH mutant and IDH wildtype glioma tissues." (PMID 37138430, 2023).
glioma (continued). "The expression of PANK1 in the high immune cell infiltration group was significantly lower than that in the low immune cell infiltration group using the M1 macrophage marker, CD86, in glioma tissues (Spearman r= -0.65, P<0.01)." (PMID 37138430, 2023). "IHC analysis showed that the level of PANK1 was significantly lower in 56 glioma tissues compared with the level in non-tumor brain tissues." (PMID 37138430, 2023). "Analysis using the four public datasets and the validation cohort showed that PANK1 expression was significantly downregulated in glioma tissues compared with non-tumor tissues (P<0.01)." (PMID 37138430, 2023). "PANK1 expression was downregulated in glioma tissues and negatively correlated with glioma malignancy." (PMID 37138430, 2023). "However, the role of PANK1 in glioma has not been fully explored." (PMID 37138430, 2023).
Hepatic steatosis (1 paper, 2022). Steatosis is a term used to denote lipid accumulation within hepatocytes. "The effect of hepatic CoA synthesis defect in promoting hepatic steatosis has been previously demonstrated in liver Pank1 knockout mice." (PMID 36171419, 2022).
Insulin resistance (1 paper, 2020). Increased resistance towards insulin, that is, diminished effectiveness of insulin in reducing blood glucose levels.
ischemic stroke (1 paper, 2022). A stroke disorder caused by obstruction of blood flow to the brain, due to thrombotic (local blood clot formation) or embolic (due to a blood clot or other material traveling from another site) event. "miR-107 is transcribed from the host gene PANK1, which is broadly expressed in many tissues and has been implicated in cancers, chemosensitivity, ischemic stroke, insulin resistance, and neuronal differentiation." (PMID 36059981, 2022).
liver disorder (1 paper, 2023). A disease involving the liver. "On the other hand, both RXRA and PANK1 are involved in signaling pathways controlling the metabolism of lipids by hepatocytes, while downregulation may contribute to serious liver disorders, such as NAFLD." (PMID 37894381, 2023).
melanoma (1 paper, 2022). A malignant, usually aggressive tumor composed of atypical, neoplastic melanocytes. "Supporting our data of miR-107 downregulation, in melanoma cell lines and melanoma tumor tissues of SKCM patients showed lower PANK1 gene expression compared to adjacent normal skin tissues." (PMID 36612285, 2022). "Further analysis confirmed that miR-107 and its host gene PANK1, but not another gene of the PANK family (PANK3) were downregulated in human and murine melanoma cell lines." (PMID 36612285, 2022).
multiple myeloma (1 paper, 2022). "In contrast, fibroblastic/stromal and endothelia or multiple myeloma cells highly expressed PANK1 and miR-107." (PMID 36612285, 2022).
Nephropathy (1 paper, 2024). A nonspecific term referring to disease or damage of the kidneys. "The discovery of peptide drugs for the treatment of CKD has attracted wide attention, with fibroin peptide notably ameliorating adriamycin-induced nephropathy by regulating lipid metabolism through the PANX1-PPARα/PANK1 pathway." (PMID 39290864, 2024).
parasitemia (1 paper, 2016). "RT-PCR analysis with similar amounts of RNA (60 ng) isolated from the same amount of blood extracted from similar infected blood parasitemia (~1%) confirmed that the transcription levels of PanK1 and PanK2 and other unrelated genes are similar in Pyp230p(−) parasites compared to WT parasites." (PMID 27644319, 2016).
prostate carcinoma (1 paper, 2021). A carcinoma that arises from epithelial cells of the prostate gland. "Moreover, microdeletions of chromosomal band 10q23.31 encompassing SLC16A12 and PANK1 have directly been associated with prostate cancer." (PMID 34573432, 2021).
renal cell carcinoma (1 paper, 2024). "PANK1 expression correlates with prognosis, tumor immunity, and metabolism in renal cell carcinoma." (PMID 38893707, 2024).
tumor (14 papers, 2016 to 2025). "Bioinformatic analysis identified PANK1 as differentially expressed between normal and tumor tissues." (PMID 38893707, 2024). "PANK1 expression significantly decreased with an increase in tumor grade in CGGA, TCGA, Gravendeel and Rembrandt datasets." (PMID 37138430, 2023). "PANK1 plays important roles in metabolism, and metabolites produced by tumor cells significantly affect tumor migration and invasion." (PMID 37138430, 2023). "MiR-107, a highly conserved miRNA that maps to intron 5 of the PANK1 gene, contributes to the regulation of normal and tumor biological processes." (PMID 33153128, 2020). "Immunohistochemical staining of the array showed that the PANK1 protein level was significantly decreased in the HCC tissues and that the levels of PANK1 protein were significantly negatively correlated with tumor size." (PMID 35280671, 2022). "Notably, MYC binding to PANK1–3 promoters is prominent in the pre-tumoral and tumor samples but absent in the matched normal tissue, suggesting a tumorigenesis-related CoA biosynthesis induction by MYC." (PMID 40832336, 2025).
cancer (12 papers, 2016 to 2025). A tumor composed of atypical neoplastic, often pleomorphic cells that invade other tissues. "PANK1 mRNA is enriched in several metabolic processes, implying that it plays a potential role in metabolic programming in cancers." (PMID 37138430, 2023). "Pantothenate kinase 1 (PANK1) mRNA is highly expressed in several metabolic processes, implying that PANK1 plays a potential role in metabolic programming in cancers." (PMID 37138430, 2023). "Currently, only a few studies have explored the role of PANK1 in cancer." (PMID 37138430, 2023). "Only a few studies have explored the role of PANK1 in cancer." (PMID 37138430, 2023). "Our investigations of PANK proteins as potential precision oncology collateral lethality targets (PANK1 is co-deleted as part of the PTEN locus in some highly aggressive cancers) were severely hindered by a dearth of commercial antibodies that can reliably detect endogenous PANK3 protein." (PMID 36139163, 2022). "Extending our observation, YO-2 exposure in a dose-dependent manner augmented the expression of miR-107 and PANK1 in human A431 and murine B16F10 cancer cells." (PMID 36612285, 2022). "Additionally, we also independently generated PANK1, PANK2, or PANK3 knockout clones in multiple different cancer cell lines to validate the band specificity and serve as a negative control for the antibodies." (PMID 36139163, 2022). "For the positive–negative subjects (screening), 3 CNAs were detected in BC genes (ACVR2A, CUL3 and PIK3R1), and 5 SNPs were identified in 6 non-BC cancer genes (SNIP1, TBC1D10B, PANK1, PRKCA and RUNX2; SUPT3H)." (PMID 35589867, 2022).
metabolic disease (3 papers, 2010 to 2024). A congenital disorder (due to inherited enzyme abnormality) or acquired (due to failure of a metabolically important organ) disorder resulting from an abnormal metabolic process. "In addition, the results distinguished the different roles of PANK1 and its intron miR‐107 in metabolic regulation, which will provide more accurate intervention targets for the treatment of metabolic diseases." (PMID 32048816, 2020).
cardiovascular disease (1 paper, 2021). "We predicted 6 candidate genes (PANK1, TRIB1, BMPR2, HDAC9, THBS1, and LARP1) that might bind to miR-942-5p and played a role in cardiovascular disease." (PMID 33869307, 2021).
PANK1 also shares sentences with these, for which no sentence is quoted: pantothenate kinase-associated neurodegeneration (3 papers); alcoholic fatty liver disease (1); chondrosarcoma (1); clear cell renal cell carcinoma (1); colorectal neoplasm (1); epithelioid cell melanoma (1); Hyperinsulinemia (1); hypertriglyceridemia (1); iron overload (1); kidney cancer (1); lung carcinoma (1); neuroblastoma (1); Obesity (1); Osteochondroma (1); pancreatic tumors (1); parasite (1); Parkinson disease (1); tuberculosis (1).